APOBEC3B (apolipoprotein B mRNA editing enzyme catalytic subunit 3B)
Diseases named in the same sentence as APOBEC3B in open-access papers (continued):
Sharing a sentence is not in itself a finding about the gene and the disease.
breast cancer (continued). "In conclusion, APOBEC3B mutagenesis is a major factor in breast cancer and many other human malignancies and much additional basic, translational, and clinical work is needed to fully realize this discovery." (PMID 25848704, 2015). "Consistent with the previous findings, only APOBEC3B shows the over-expression in the range of two- to fourfold changes in breast cancer cells relative to normal cells." (PMID 26682542, 2015). "The transcriptome data from both breast cancer cell lines and tumor specimens reveal that the APOBEC3B and APOBEC3C genes show significant differences at the transcription levels between ER+ and ER− breast tumors." (PMID 26682542, 2015). "In the analysis of the CNV status of APOBEC3B in 787 breast tumor samples, we detected 190 breast cancer samples in carriers of germline deletion of APOBEC3B gene." (PMID 26682542, 2015). "For example, we observed that the elevated expression levels of APOBEC3C but lowered expression levels of APOBEC3B in breast cancer patients have better clinical outcomes." (PMID 26682542, 2015). "The mutation data obtained in yeast reveal APOBEC3B and APOBEC3A as the only deaminases characterized whose target specificity matches the breast cancer kataegic mutations, strongly suggesting involvement of these deaminases in cancer kataegis." (PMID 24748981, 2014). "In line with this is our observation of a HR of 1.57 for APOBEC3B overexpression in luminal A breast cancer (Supplementary analysis), which is considered an M class cancer driven by mutations rather than copy number aberrations." (PMID 25123150, 2014). "Recent observations connected DNA cytosine deaminase APOBEC3B to the genetic evolution of breast cancer." (PMID 25123150, 2014). "APOBEC3B is a marker of pure prognosis and poor outcomes for ER + breast cancer, which strongly suggests that genetic aberrations induced by APOBEC3B contribute to breast cancer progression." (PMID 25123150, 2014). "In contrast, APOBEC3B-elevated mutagenesis in breast cancer is more modest, appearing to occur gradually after the initial tumor has formed." (PMID 25123150, 2014). "Bladder, cervical, lung squamous cell carcinoma, lung adenocarcinoma, head and neck, and breast cancers shared a strong bias for TCN (N = A or C or G or T) mutation signatures, as observed for the recombinant APOBEC3B protein." (PMID 24705290, 2014). "The combined results indicate that high levels of APOBEC3B mRNA expression are a significant prognostic biomarker of poor breast cancer outcomes, exclusively in cases with ER-positive primary disease." (PMID 25123150, 2014). "APOBEC3B messenger RNA (mRNA) levels were related in 1,491 primary breast cancers to disease-free (DFS), metastasis-free (MFS), and overall survival (OS)." (PMID 25123150, 2014). "For example, APOBEC3B mRNA was found to be upregulated relative to controls in 28/38 established breast cancer cell lines and to be expressed in the nucleus." (PMID 24705290, 2014). "Together with expression and functional assays, the results implicate APOBEC3B/A in breast cancer hypermutation and give insight into the mechanism of kataegis." (PMID 23599896, 2013). "The mutation data obtained in yeast reveal APOBEC3B and APOBEC3A as the only deaminases characterised whose target specificity matches the breast cancer kataegic mutations, arguing very strongly for an involvement of these deaminases in cancer kataegis." (PMID 23599896, 2013). "RNA analysis revealed that although several APOBEC3s can be expressed in individual breast cancer cell-lines, the highest and broadest pattern of expression was evident with APOBEC3B." (PMID 23599896, 2013). "K. Ohba and colleagues investigated whether carcinogenic human papillomavirus could be an inducing factor in breast cancer development by triggering APOBEC3B overexpression, thus serving as the missing link between HPV and breast cancer progression." (PMID 41602431, 2026).
breast cancer (continued). "APOBEC3B is also expressed as breast cancer cell lines approach mitosis, and its knockdown slows proliferation, suggesting a role in cell cycle progression that might be linked to its function as a transcriptional co-activator for the oestrogen receptor." (PMID 39548236, 2025). "APOBEC3B (A3B) has been implicated in driving genetic heterogeneity in cancers by inducing C > T transitions and C > G transversions at 5’-TCW motifs (W = A or T), a mutation pattern observed in more than 50% of primary breast cancers." (PMID 39322638, 2024). "High APOBEC3B expression was also associated with more APOBEC3-induced mutations in lung cancer, while both APOBEC3A and APOBEC3B levels were correlated with APOBEC3-induced mutations in breast cancer." (PMID 36978147, 2023). "We compared the clinical characteristics of the patients with breast cancer with and without the APOBEC3B mutation." (PMID 37510234, 2023). "A large germline deletion of the APOBEC3B gene was reported as a low-risk variant for breast cancer, but negative reports have also been published." (PMID 37510234, 2023). "Breast cancer samples with higher APOBEC3A expression had significantly more APOBEC-driven SGMs compared to cancers with lower expression (P = 1.3 × 10−6, Wilcoxon test) while weaker or subsignificant associations were seen with APOBEC3B expression." (PMID 37922356, 2023). "Interestingly, the proteomics data suggested lower expression of the APOBEC3B protein in breast cancer and LUAD, opposite of that observed at the mRNA level." (PMID 35918642, 2022). "Increasing research has shown that APOBEC3B may be a predominant mutagenic factor influencing the occurrence and evolution of various cancers such as breast cancer, gastric cancer, chondrosarcoma, hepatocellular carcinoma, and so on." (PMID 36249021, 2022). "APOBEC3B is the most common member of the family, and it is involved in the development of cancer, including liver cancer, breast cancer, gastric cancer, chondrosarcoma, kidney cancer, colorectal cancer, cervical squamous cell carcinoma, lung cancer, and bladder cancer." (PMID 36203448, 2022). "In many studies, KPNA2 has been linked to tumorigenesis (such as non-small cell lung cancer, breast cancers, and epithelial ovarian cancer), and the gene is highly expressed in many cancerous tissues, which is consistent with the expression of the APOBEC3B gene in this study." (PMID 35918642, 2022). "APOBEC3B levels are higher in breast cancer cell lines and patient samples." (PMID 36405752, 2022). "Examples include, among others, APOBEC3B in breast cancer or AID in B cell lymphoma." (PMID 35955853, 2022). "In an in vitro study, the MCF-10A cell line was transfected with HPV-18 to determine whether HPV may be the starting point of carcinogenesis in breast cancer through APOBEC3B (A3B) overexpression." (PMID 36005146, 2022). "Alternatively, AID and ORF2p might be independently driven to specific DNA regions through a direct binding with AR, as hypothesised for APOBEC3B and the oestrogen receptor in a breast cancer model." (PMID 33121045, 2020). "Since APOBEC3B is a gain-of-function mutagenic enzyme, patients could benefit from the therapeutic targeting of APOBEC3B in the early non-invasive stage of breast cancer." (PMID 31357602, 2019). "Since APOBEC3B is a gain-of-function mutagenic enzyme, it could be a candidate for therapeutic targeting in an early, non-invasive stage of breast cancer." (PMID 31357602, 2019). "APOBEC3B has been identified as an important factor in the evolution of breast cancer." (PMID 31357602, 2019). "We believe this could improve breast cancer care in the future since APOBEC3B is a gain-of-function mutagenic enzyme, so patients could potentially be treated with small molecules at a very early, non-invasive stage." (PMID 31357602, 2019). "Taken together, these studies suggest that the APOBEC family and particularly APOBEC3B may play a central role in the early stages of breast cancer induction." (PMID 29404275, 2018).
breast cancer (continued). "It was also suggested that APOBEC3B may be a potential prognostic marker and therapeutic target for breast cancer." (PMID 29853799, 2018). "Furthermore, elevated APOBEC3B expression is correlated with a declined efficacy of tamoxifen (TAM) therapy in recurrent ER + breast cancer patients." (PMID 29853799, 2018). "However, despite various efforts, we had to conclude that detecting APOBEC3B in breast cancer by immunohistochemistry with these currently commercially available antibodies should be considered unreliable due to non-specific staining." (PMID 28141868, 2017). "Therefore, we set out to evaluate APOBEC3B mRNA expression in primary breast cancer and matched metastases." (PMID 28141868, 2017). "APOBEC3B is thought to affect the evolution of breast cancer by somatically mutagenizing the cancer genome, which could potentially be abrogated by therapeutic intervention." (PMID 28141868, 2017). "This is especially noteworthy in view of our previous finding, that high levels of APOBEC3B were only associated with poor prognosis in ESR1-positive primary breast cancers, and not in ESR1-negative cases." (PMID 28141868, 2017). "In this current, more concise study with a special focus on breast cancer metastases, we only observed a negative association between APOBEC3B and ERBB2 mRNA levels in both the primary tumor and the metastases (data not shown)." (PMID 28141868, 2017). "Besides, multiple studies have postulated that APOBEC3B influences the development of metastases and drug resistance, especially in estrogen receptor alpha (ERα)-positive breast cancer." (PMID 28141868, 2017). "In breast cancer, APOBEC3B upregulation correlated with increased levels of transition mutations, suggesting that a proportion of the genomic uracils created by APOBCE3B either persist through DNA synthesis or are generated at a high enough rate that they are detectable in non-replicated DNA." (PMID 28572915, 2017). "We showed a lack of association of the APOBEC3B deletion with breast and/or ovarian risk (for the first time including familial breast cancer), which was independently validated in three European cohorts (in total: 2972 cases and 3682 controls)." (PMID 29100317, 2017). "Furthermore, brain tumors (low-grade glioma, glioblastoma multiforme) and ovarian tumors (serous cystadenocarcinoma) also had lower APOBEC3B expression levels than breast carcinoma." (PMID 28141868, 2017). "Also, APOBEC3B has recently been verified to be a marker of pure prognosis and poor outcomes for ER+ breast cancer, which strongly suggests that genetic aberrations induced by APOBEC3B contribute to breast cancer progression." (PMID 27602762, 2016). "The predictive value of the APOBEC3B deletion was assessed among 329 ER-positive breast cancer patients who received tamoxifen as the first-line therapy for recurrent disease and 226 breast cancer patients who received first-line chemotherapy for recurrent disease." (PMID 27552096, 2016). "Epidemiological combined with experimental data have demonstrated that (i) the prevalence of high-risk HPVs is high in early as compared to late breast cancer, (ii) this early influence of HPVs is indirect and operates by the destabilizing effects of HPV on the human genome via APOBEC3B enzyme." (PMID 27747193, 2016). "Thus, APOBEC3B is a marker of poor prognosis for ER+ breast cancer, which strongly suggests that genetic aberrations induced by APOBEC3B contribute to breast cancer progression or resistance to treatment." (PMID 27977754, 2016). "Next, we evaluated whether calculated APOBEC3B copy number values could predict the outcome of first-line chemotherapy in a cohort of 226 breast cancer patients." (PMID 27552096, 2016). "APOBEC3B is overexpressed in several human cancer types, including breast cancer." (PMID 27977754, 2016).
breast cancer (continued). "Notably, breast cancers with at least one-copy APOBEC3B deletion had lower fraction of macrophages M2 compared to A3Bwt/wt breast cancers with mean fractions of 0.196 and 0.207, respectively, but this difference was only marginally significant (P = 0.04)." (PMID 27233495, 2016). "Indeed, immune response-related gene sets were found to be enriched in breast cancers arising from APOBEC3B deletion carriers." (PMID 27233495, 2016). "On the other hand, a germ-line deletion polymorphism in APOBEC3B, which leads to no expression of APOBEC3B, has been associated with an increased risk of breast cancer." (PMID 27977754, 2016). "In addition, a 29.5 kb deletion polymorphism of APOBEC3B, resulting in an APOBEC3A-B hybrid transcript, has been associated with an increased breast cancer risk and the hypermutator phenotype." (PMID 27552096, 2016). "In breast cancer specifically APOBEC3B has been identified as highly mutagenic." (PMID 26926109, 2016). "Moreover, nearly two-thirds of all breast cancer cell lines showed upregulated levels of APOBEC3B in comparison with control lines such as MCF10A." (PMID 25848704, 2015). "Therefore, the most parsimonious explanation at this time is that APOBEC3B and at least one additional family member contribute to mutagenesis in breast cancer." (PMID 25848704, 2015). "APOBEC3B may be of similar importance to breast cancer, and one can already envisage developing the equivalent of a ‘sunscreen’ to inhibit APOBEC3B mutagenesis." (PMID 25848704, 2015). "Interestingly, the isoforms of the apolipoprotein B mRNA-editing enzyme catalytic polypeptide-like (APOBEC3A, APOBEC3B and APOBEC3H), implicated in breast cancer carcinogenesis, were also up-regulated." (PMID 25961742, 2015). "False positive breast cancer diagnoses still occur and molecular information on APOBEC3B may help reduce the magnitude of this problem." (PMID 25848704, 2015). "The prognostic value of APOBEC3B was especially prominent in ER + disease, suggesting that particularly in this subclass of breast cancer levels of APOBEC3B may contribute to cancer progression." (PMID 25123150, 2014). "APOBEC3B mRNA expression levels were quantified in the Rotterdam cohort (n = 1,491) by RT-qPCR of total RNA samples extracted from freshly frozen tumor tissues from patients with primary breast cancer." (PMID 25123150, 2014). "However, also in patients receiving various types of adjuvant endocrine and/or chemotherapy, the analysis came out as significant, suggesting that overall, the APOBEC3B enzyme contributes to breast cancer progression." (PMID 25123150, 2014). "As a potential continuous source of genetic aberrations in breast cancer, we hypothesized that APOBEC3B overexpression may accelerate cancer progression and lead to poor clinical outcomes." (PMID 25123150, 2014). "Although kataegis could easily have resulted from a transient spike in deaminase expression during tumour development, it was interesting to ascertain whether APOBEC3A or APOBEC3B expression could be detected or induced in breast cancer-derived cells." (PMID 23599896, 2013). "While one GWAS did not detect a significant association for breast cancer in European patients another one detected a significant association with a common APOBEC3B deletion in Chinese breast cancer patients." (PMID 24025454, 2013). "Consistent with studies in other cell-types, the expression of APOBEC3A and APOBEC3B in some of the breast cancer cell-lines could be enhanced by treatment with phorbol ester or interferon alpha." (PMID 23599896, 2013).
breast cancer (continued). "No particular cancer was seen in excess in the relatives of the APOBEC3B mutation carriers, compared to those of non-carriers, including cancers of the breast, prostate, colon, kidney, lung, larynx, pancreas, stomach, cervix, endometrium, ovary, leukemia and lymphoma." (PMID 37510234, 2023). "Then, we genotyped approximately 12,500 unselected cases of breast cancer and 3700 cancer-free controls for the c.783delG founder mutation and compared the clinical characteristics of breast tumors in carriers of the APOBEC3B mutation with cancers diagnosed among non-carriers." (PMID 37510234, 2023). "To investigate whether or not germline intragenic mutations of APOBEC3B are present the Polish population and predispose to breast cancer, we studied approximately 13,000 patients with breast cancer and 3700 controls." (PMID 37510234, 2023). "We also investigated whether or not breast cancers in women with APOBEC3B mutations are associated with specific clinical characteristics and survival among patients." (PMID 37510234, 2023). "We then analyzed the pedigrees of breast cancer patients with the APOBEC3B mutation to see whether or not there is an excess of different cancers in first- and second-degree relatives." (PMID 37510234, 2023). "We conclude the APOBEC3B deleterious mutation p.Val262Phefs does not confer breast cancer risk." (PMID 37510234, 2023). "In the current study, we asked whether or not APOBEC3B mutations are present in Poland and whether they predispose to breast cancer." (PMID 37510234, 2023). "To investigate whether or not APOBEC3B is a breast cancer susceptibility gene, we sequenced this gene in 617 Polish patients with hereditary breast cancer." (PMID 37510234, 2023). "Our study showed that the isoforms uc003awn (APOBEC3A) and uc003awo (APOBEC3B) were independently associated with a higher burden of APOBEC-mutational signature in multiple cancer types, while such an association for the uc011aoc (APOBEC3A/B) was only observed in breast cancer." (PMID 31533728, 2019). "In a study we performed earlier, we observed higher mRNA levels of APOBEC3B in breast cancer metastasis as compared to the corresponding primary tumor, supporting our hypothesis that, already starting from DCIS, breast cancer progression is associated with deregulated expression of APOBEC3B." (PMID 31357602, 2019). "APOBEC3A expression was not initially detectable in breast cancer cell lines, and APOBEC3B expression correlates strongly with overall mutations in multiple malignancies, leading many to initially believe that APOBEC3B is responsible for the majority of the APOBEC mutational signature." (PMID 29435122, 2018). "To obtain a more global view on the effect of the APOBEC3B deletion on cancer, we conducted a comprehensive meta-analysis that considered all case-control studies of the deletion (including our own) performed using cases with different cancer types (predominantly breast cancer)." (PMID 29100317, 2017). "However, the expression of APOBEC3B in breast cancer metastases remained to be elucidated." (PMID 28141868, 2017). "Taken together, we propose that tumour-infiltrating immune cells may be an important feature of breast cancers arising in women with APOBEC3B germline deletions and that this may be of particular interest in Asian women where the germline deletion is more common." (PMID 27233495, 2016). "However, our analysis of breast cancer gene expression data shows clearly that the correlates of APOBEC3B expression in tumors (proliferation) are distinct from all of the other members of the APOBEC3 family, which are very strongly associated with a STAT1/interferon signature." (PMID 27716362, 2016). "However, we were able to demonstrate that high APOBEC3B mRNA expression is associated with the aggressiveness of breast cancer and a poor prognosis in ER+ breast cancer, regardless of ethnic difference." (PMID 27977754, 2016).